RBMX (RNA binding motif protein X-linked)
Description:
RNA-binding protein that plays several role in the regulation of pre- and post-transcriptional processes. Implicated in tissue-specific regulation of gene transcription and alternative splicing of several pre-mRNAs. Binds to and stimulates transcription from the tumor suppressor TXNIP gene promoter; may thus be involved in tumor suppression. When associated with SAFB, binds to and stimulates transcription from the SREBF1 promoter. Associates with nascent mRNAs transcribed by RNA polymerase II. Component of the supraspliceosome complex that regulates pre-mRNA alternative splice site selection. Can either activate or suppress exon inclusion; acts additively with TRA2B to promote exon 7 inclusion of the survival motor neuron SMN2. Represses the splicing of MAPT/Tau exon 10. Binds preferentially to single-stranded 5'-CC[A/C]-rich RNA sequence motifs localized in a single-stranded conformation; probably binds RNA as a homodimer. Binds non-specifically to pre-mRNAs. Also plays a role in the cytoplasmic TNFR1 trafficking pathways; promotes both the IL-1-beta-mediated inducible proteolytic cleavage of TNFR1 ectodomains and the release of TNFR1 exosome-like vesicles to the extracellular compartment.
Synonyms: HNRPG; RNMX; hnRNP-G; HNRNPG; MRXS11; MRXSG; MRXSH; RBMXRT
Tractability: PROTAC: UniProt records ubiquitination sites on it; ubiquitination databases record sites on it; its protein half-life has been measured.
Gene: Protein-coding gene on chromosome X (136,848,004 to 136,880,764, reverse strand). Ensembl gene ENSG00000147274.
Subcellular location: Nucleus
Subcellular location (Human Protein Atlas): Nucleoplasm
Pathways (Reactome):
Signal Transduction: RHOBTB1 GTPase cycle; RHOBTB2 GTPase cycle; RND1 GTPase cycle; RND2 GTPase cycle; RND3 GTPase cycle
Metabolism of RNA: Processing of Capped Intron-Containing Pre-mRNA; mRNA Polyadenylation; mRNA Splicing - Major Pathway
Disease: Dengue Virus-Host Interactions
Gene Ontology:
Molecular function: chromatin binding; identical protein binding; mRNA binding; protein binding; protein domain specific binding; RNA binding; RNA polymerase II cis-regulatory region sequence-specific DNA binding; nucleic acid binding
Biological process: cellular response to interleukin-1; membrane protein ectodomain proteolysis; osteoblast differentiation; positive regulation of transcription by RNA polymerase II; regulation of alternative mRNA splicing, via spliceosome; transcription by RNA polymerase II; mRNA splicing, via spliceosome; negative regulation of mRNA splicing, via spliceosome; positive regulation of mRNA splicing, via spliceosome; protein homooligomerization
Cellular component: catalytic step 2 spliceosome; euchromatin; extracellular exosome; extracellular region; membrane; nucleoplasm; nucleus; protein-containing complex; supraspliceosomal complex; ribonucleoprotein complex; spliceosomal complex
Homologues: Orthologues: chimpanzee RBMX (100% identical), dog RBMX (100% identical), guinea pig RBMX (99% identical), macaque RBMX (99% identical), mouse Rbmx (99% identical). Paralogues in human: RBMXL1 (95% identical), RBMXL2 (73% identical), RBMY1B (61% identical), RBMY1F (61% identical), RBMY1J (61% identical), RBMY1A1 (61% identical), RBMY1D (61% identical), RBMY1E (61% identical), RBMXL3 (56% identical), CIRBP (29% identical), MSI1 (24% identical), MSI2 (24% identical), and 24 more.
Diseases named in the same sentence as RBMX in open-access papers:
RBMX is named in the same sentence as 72 diseases in open-access papers, as found by Europe PMC text mining. Sharing a sentence is not in itself a finding about the gene and the disease. The quoted sentences say what the papers report.
bladder cancer (9 papers, 2021 to 2025). "This gene has been linked to poor survival in bladder cancer, and tobacco-induced mutations in RBMX are thought to predispose individuals to lung cancer." (PMID 40430005, 2025). "RBMX is a chromosome-x-linked RNA binding motif protein, which has also been associated with bladder cancer and kidney cancer." (PMID 35053577, 2022). "In contrast, in bladder cancer, RBMX exhibits an oncogenic effect by inhibiting hnRNP A1-mediated PKM splicing." (PMID 40692788, 2025). "The most thoroughly researched RBM protein in bladder cancer is RBMX, which is a ubiquitously expressed nuclear RNA-binding protein." (PMID 39132499, 2024). "Previous research verified that low RBMX expression is related to poor prognosis in endometrial cancer and bladder cancer." (PMID 38214653, 2024). "By inhibiting hnRNPA1-dependent PKM splicing and consequent PKM2 overexpression, RBMX neutralizes the aggressive phenotype of metastatic bladder cancer cells." (PMID 38785973, 2024). "With low expression in metastatic bladder cancer tissues, RBMX can competitively bind to the RGG motif of hnRNPA1 and block it from combining with the lateral intron of PKM mRNA exon 9, leading to high expression of PKM1 and weakening the malignancy and progression of tumors." (PMID 38785973, 2024). "Similarly, RBMX has been proved to inhibit the development of bladder cancer cells." (PMID 36338999, 2022). "Several RBM proteins have been studied in the context of bladder cancer, including RBM3, RBM10, RBM24, RBM5, and RBMX." (PMID 39132499, 2024). "Additionally, RBMX inhibits aerobic glycolysis via hnRNP-A1-dependent PKM alternative splicing, and it counteracts the aggressive phenotype induced by PKM2 overexpression in bladder cancer cells." (PMID 39132499, 2024).
hepatocellular carcinoma (8 papers, 2021 to 2025). A malignant tumor that arises from hepatocytes. "However, high expression of RBMX has also been associated with poor prognosis in hepatocellular carcinoma (HCC)." (PMID 38214653, 2024). "Increased expression of RBMx was observed in hepatocellular carcinoma (HCC) patient tissue and HCC cell lines." (PMID 38328550, 2024). "RBMX serves as therapeutic target for hepatocellular carcinoma, because it promotes hepatocellular carcinoma development and reduce sorafenib sensitivity by targeting BLACAT1." (PMID 37194014, 2023). "RBM15 and RBMX facilitate the proliferation and invasiveness of tumors, such as hepatocellular carcinoma." (PMID 36171892, 2022). "RBMX is significantly contributes to the tumorigenesis and sorafenib resistance of hepatocellular carcinoma." (PMID 34804951, 2021). "In hepatocellular carcinoma (HCC) and T-cell lymphoma, elevated RBMX expression enhances tumor progression and chemoresistance by stabilizing oncogenic long non-coding RNAs (lncRNAs), such as BLACAT1, or modulating RNA metabolism." (PMID 40692788, 2025). "In contrast, recent studies interestingly show poor outcome in hepatocellular carcinomas (HCC) as well as head and neck cancers when RBMX was highly expressed." (PMID 34638274, 2021).
breast carcinoma (6 papers, 2015 to 2025). "Previous studies show that all X-chromosome-located RBMX genes are significantly up-regulated in breast cancer and correlate positively with the expression of the pro-apoptotic gene, BAX." (PMID 37805597, 2023). "Literatures exist showing that RBMX predicted prognosis in patients with head and neck cancer and regulated apoptosis in breast cancer." (PMID 33343639, 2020). "In this study, we have further validated the potential therapeutic value of this packaging mechanism, RBMX silencing efficiently prevented BCC-elicited DOXIC aggravating effects by blocking the adverse communication between breast cancer cells and cardiomyocytes." (PMID 40915108, 2025). "By comparing tumor and normal samples, we found that six proteins were differentially expressed in breast cancer significantly (P < 0.001), including EIF3A, HNRNPA2B1, HNRNPC, RBMX, YTHDF1, YTHDF2." (PMID 33585234, 2020).
lung carcinoma (6 papers, 2021 to 2025). "In the case of RBMX, it has been proposed as a potential therapeutic target in lung cancer due to its association with telomere instability, and its depletion has been shown to sensitize tumor cells to cytotoxic agents." (PMID 40430005, 2025). "Truncation mutations of RBMX identified in lung cancer suggest it as a potential tumor suppressor gene." (PMID 39036344, 2024). "In genome sequencing in lung cancer patients, mutations truncating the RBMX gene are identified, probably induced by tobacco smoke." (PMID 37756323, 2023). "Genome sequencing has been used to identify truncation mutations of the RBMX gene in lung cancer patients, suggesting RBMX as a potential tumor suppressor." (PMID 33564070, 2021). "RBMX mutations induced by cigarettes smoking may drive lung cancer development in smokers." (PMID 39036344, 2024). "Tobacco-induced mutations in RBMX may predispose smokers to developing lung cancer." (PMID 33564070, 2021). "We also looked at the protein levels of RBMX, METTL16, and LRPPRC in lung cancer cells and discovered that RBMX and LRPPRC were upregulated, whereas METTL16 was downregulated in lung cancer cells relative to normal lung epithelial cell BEAS-2B." (PMID 35035657, 2022).
leukemia (4 papers, 2021 to 2024). A malignant (clonal) hematologic disorder, involving hematopoietic stem cells and characterized by the presence of primitive or atypical myeloid or lymphoid cells in the bone marrow and the blood. "CBX5 was reported to had higher expression in high than in low c-Kit leukemia stem cell populations, and elevated CBX5 expression was associated with increased expression of RBMX and RBMXL1, which maintain the chromatin state essential for the survival of acute myeloid leukemia cells." (PMID 38798352, 2024). "For instance, RBPs directly regulate transcription in leukemia cells such as RBMX." (PMID 38216972, 2024). "Furthermore, RBMX was overexpressed in individuals with acute myeloid leukemia (AML) compared to healthy ones, and loss of RBMX delayed leukemia development." (PMID 34638274, 2021). "RBMX and RBMXL1 could contribute to leukemia develop_x005fment and maintenance." (PMID 34804951, 2021).
lung adenocarcinoma (4 papers, 2023 to 2025). A carcinoma that arises from the lung and is characterized by the presence of malignant glandular epithelial cells. "LINC00273 efficiently increased the interactions between miR-19b-3p and RBMX in lung adenocarcinoma cells." (PMID 37568787, 2023). "The knockdown of RBMX impaired the delivery of exosomal miR-19b-3p from lung adenocarcinoma cells to THP1 (Mφ) cells." (PMID 37568787, 2023). "Similarly, a previous study revealed that RBMX bound to miR-19b-3p to facilitate the packaging of miR-19b-3p into lung adenocarcinoma cell-derived exosomes." (PMID 40915108, 2025). "Additionally, both RBMX and PDE4D have been proposed as potential predictors of response to immunotherapy in patients with lung adenocarcinoma." (PMID 40430005, 2025).
liver cancer (3 papers, 2022 to 2024). An epithelial or non-epithelial malignant neoplasm that arises from the liver. "The results showed that the ability of the two liver cancer cell lines for colony formation was significantly decreased following the knockdown of RBMX expression." (PMID 38214653, 2024). "The results showed that knockdown of RBMX can impair the proliferation, migration, and invasion of liver cancer cells." (PMID 38214653, 2024). "We also aimed to determine the potential biological functions of RBMX in liver cancer cells." (PMID 38214653, 2024). "Therefore, we conducted a fluorescence immunohistochemistry assay to detect RBMX and CD11b in three liver cancer samples." (PMID 38214653, 2024). "Finally, by knocking down RBMX using short hairpin RNAs (shRNAs), we also validated the vital role of RBMX in maintaining the proliferative, migrative, and invasive capacities of liver cancer cells." (PMID 38214653, 2024).
melanoma (3 papers, 2017 to 2024). A malignant, usually aggressive tumor composed of atypical, neoplastic melanocytes. "For the first time, we have reported a frameshift variant of RBMX in melanoma." (PMID 31936151, 2020). "The results indicated the important role of RBMX in predicting the efficacy of ICIs in the treatment of melanoma." (PMID 38214653, 2024). "The role of RBMX protein in inhibiting the PI3K/AKT pathway in melanoma, especially the functional inability of a frameshift variant S303 of RBMX to exert this function, needs a further investigation." (PMID 31936151, 2020). "Several de novo mutations (G379R, Y357H, R339G, S337N, S303 frameshift) in RBMX that span the RNA-interacting domain of RBMX were found in our study, but only one of them S303fs+/− was present in resistant melanoma cell lines with elevated activity of AKT (21_TRAR, 28_TRAR, 29_PLXR)." (PMID 31936151, 2020).
ovarian carcinoma (3 papers, 2016 to 2023). A malignant neoplasm originating from the surface ovarian epithelium. "GSEA analysis demonstrated that the expressions of METTL3, YTHDC1, RBM15B, HNRNPC, IGF2BP2, RBMX, and ZC3H13 were correlated with a higher number of multiple Hallmark pathways in ovarian cancer." (PMID 33225598, 2021). "Interestingly, it is reported that RBMX was present in exosomes isolated from ovarian cancer cells and endothelial cells." (PMID 37756323, 2023). "Given the theory implicating the distal oviduct as a common source for epithelial ovarian cancer, we analyzed the GSE69428 data and showed that the expression of IGF2BP2, IGF2BP3, RBMX, YTDHF1, and RBM15 was also higher in ovarian cancer than in normal oviduct." (PMID 33225598, 2021). "Two GEO databases demonstrated that 7 readers (HNRNPC, IGF2BP1, IGF2BP2, IGF2BP3, RBMX, YTHDC2, and YTHDF2) and 3 writers (METTL3, RBM15, and RBM15B) were more highly expressed in ovarian cancer than in ovarian surface epithelium or normal peritoneum tissues (GEO14407 and GEO12470)." (PMID 33225598, 2021).
pancreatic cancer (3 papers, 2015 to 2024). "Furthermore, pancreatic cancer patients with lower METTL3, METTL14, RBMX, FTO, ALKBH5, YTHDF1, and YTHDC1 mRNA expression levels or higher VIRMA, HNRNPA2B1, EIF3A, IGF2BP1, IGF2BP2, and IGF2BP3 mRNA expression levels had significantly poorer OS (P < 0.05)." (PMID 34330301, 2021). "It is revealing that the depletion of RBMX, EWS, FUS, SKIP and Tra2 all augment DNA damage-induced apoptosis, and that knocking down PTBP1 abolishes resistance to genotoxic drugs in pancreatic cancer cells." (PMID 26529031, 2015).
prostate carcinoma (3 papers, 2021 to 2024). A carcinoma that arises from epithelial cells of the prostate gland. "The expressions of two m6A-RMRs such as EIF3A and RBMX were upregulated in prostate carcinoma samples compared with normal prostate epithelium-adjacent samples." (PMID 35211628, 2022). "Some researchers analyzed the important m6A RNA regulators, which act as prognosis factors in prostate cancer, and identified RBMX, NXF1, YTHDF1, HNRNPA2B1, and TRMT112 as critical genes that have great effects on the prognosis of PCa patients." (PMID 34899855, 2021).
T-cell lymphoma (3 papers, 2021 to 2025). "In a recent study, RBMX (acting as a protein connector) was strongly correlated with T-cell lymphoma progression and chemotherapy response." (PMID 38214653, 2024). "The study identifies low RBMX expression to predict better chemotherapy response, overall survival and progression-free survival in patients with T-cell non-Hodgkin’s lymphomas." (PMID 34638274, 2021). "To the best of our knowledge, we present the first analysis of the prognostic impact of RBMX protein expression in patients with T-cell lymphomas." (PMID 34638274, 2021). "In this study, we investigated the immunohistochemical expression of RBMX in combination with the clinical outcomes in 53 patients with T-cell non-Hodgkin’s lymphomas." (PMID 34638274, 2021). "In conclusion, our study found that low RBMX protein expression predicted better response to anthracycline-containing first-line treatment, overall survival, and progression-free survival in patients with T-cell non-Hodgkin’s lymphomas." (PMID 34638274, 2021). "In conclusion, this study showed that low RBMX expression was associated with better response to anthracycline-containing first-line treatment and an improved overall survival (OS) and progression-free survival (PFS) in patients with T-cell non-Hodgkin’s lymphomas." (PMID 34638274, 2021). "Hence, RBMX may be a potential therapeutic target and prognostic marker in T-cell lymphomas." (PMID 34638274, 2021). "Hence, RBMX may be a potential therapeutic target and prognostic marker in T-cell lymphoma." (PMID 34638274, 2021). "RBMX expression was examined in normal non-tumor lymph node tissue and T-cell lymphoma, showing lower expression in healthy tissues compared to tumor samples with high RBMX expression (non-tumor vs. RBMXhigh: mean 150 (SD = 49) vs. 220 (SD = 44); p = 0.024)." (PMID 34638274, 2021).
endometrial cancer (2 papers, 2021 to 2024). Primary or metastatic malignant neoplasm involving the endometrium (mucous membrane that lines the endometrial cavity). "Increased levels of RBMX expression are associated with a favorable outcome for patients with endometrial cancer." (PMID 33564070, 2021).
esophageal cancer (2 papers, 2025). A primary or metastatic malignant neoplasm involving the esophagus. "Research by Tuersun and Bei has emphasized that RBMX is a significant prognostic biomarker in various cancers, including esophageal cancer, where its expression correlates with tumor progression and poor clinical outcomes." (PMID 40692788, 2025). "The results showed that COL4A1, DEK, GINS1, HPCAL1, KIF4A and RBMX were significantly increased in esophageal cancer tissues and decreased in the combined treatment group, suggesting that are potential prognostic markers." (PMID 41326355, 2025). "Decreased levels of COL4A1, DEK, GINS1, HPCAL1, KIF4A and RBMX predicted longer survival in esophageal cancer patients, while overexpression of IGFL1P1, LRRC57A-AS1, SNHG3, ULK3 and ZFYVE19 correlated with longer survival." (PMID 41326355, 2025). "The interaction of RBMX with splicing factors such as TRA2A and hnRNP A1 offers deeper insights into the regulatory networks governing esophageal cancer progression." (PMID 40692788, 2025). "Investigating how RBMX influences alternative splicing and m6A methylation, particularly in relation to other RNA-binding proteins such as TRA2A, may reveal new insights into the biology of esophageal cancer and resistance to therapies like sorafenib." (PMID 40692788, 2025).